MTOR (mechanistic target of rapamycin kinase)
Diseases named in the same sentence as MTOR in open-access papers (continued):
Sharing a sentence is not in itself a finding about the gene and the disease.
kidney disease (94 papers, 2012 to 2026). "The correlation between polymorphisms in mTOR pathway genes and kidney disorders has been extensively documented in numerous studies." (PMID 38958113, 2024). "It was reported that in the glucose induced kidney disease or caused by the higher glucose level the oxidative stress suppressed by the mi-RNA 214 by the uncoupling protein and reactive oxygen species or Akt/mTOR pathway." (PMID 33260422, 2020). "Impaired activity of mTOR complexes (mTORC1/mTORC2), particularly mTORC1 overactivation, has been implicated in a plethora of age-related disorders, including human renal diseases." (PMID 30510618, 2018). "Previously, the mammalian target of rapamycin (mTOR) was linked to actin regulation and aberrant activity of the kinase was associated with renal disease." (PMID 23418489, 2013). "However, recent studies showed the suppressive efficacy of mTOR inhibitor on the onset of BK virus-associated nephropathy." (PMID 27338360, 2016). "Activation of mTOR signaling is also associated with several common forms of kidney disease, suggesting that inhibition of mTOR might have broader therapeutic benefits for kidney health." (PMID 24379984, 2013). "mTOR is a serine/threonine protein kinase belonging to the phosphatidylinositol-associated protein kinase family, which regulates cell growth, metabolism, proliferation, and survival, and plays an important role in the signaling pathway network related to kidney disease." (PMID 40916492, 2025). "It has been demonstrated that HCQ builds the action of mTOR inhibitors; for example, everolimus in cell lines comes from renal disease." (PMID 38707383, 2024). "Remarkably, high number of previously reported kidney disease genes showed intrinsic sexual dimorphism and/or different response patterns towards mTOR inhibition." (PMID 39278930, 2024). "Rapamycin, an mTOR pathway inhibitor, has been investigated for treating various kidney diseases, but it has been mainly restricted to kidney transplantation and tuberous sclerosis disorders due to its potential nephrotoxicity." (PMID 38842935, 2024). "Published reports have shown therapeutic benefits of suppressing the mTOR and AhR signaling pathways in the treatment of kidney diseases, including DN." (PMID 39902076, 2024). "Previous studies have reported that the AKT/mTOR pathway is highly involved in the regulation of autophagy in kidney disease." (PMID 37443810, 2023). "Additional strengths include application of spatial metabolomics and single-cell transcriptomics to identify a pathway linking adenine to mTOR in human kidney disease pathology and progression." (PMID 37616058, 2023). "Several published studies in mice and rats have also found that inhibiting mTOR protects against adenine-induced kidney disease." (PMID 37616058, 2023). "Mammalian target of rapamycin (mTOR) is a complex of protein kinase signal molecules that promote kidney disease." (PMID 37759585, 2023). "Both mTOR and α-klotho play a role in the pathophysiology of renal disease, influence mineral metabolism and participate in the aging process." (PMID 38015969, 2023). "Emerging data have reported that the PI3K/AKT/mTOR pathway is closely related to kidney diseases via regulating autophagy." (PMID 36081940, 2022). "A growing number of studies have shown that the mTOR signaling pathway is an important regulator of podocyte homeostasis and tubelar transportation in renal diseases." (PMID 35149934, 2022). "Metabolic pathways, such as mitochondrial function, glycolysis, lipid synthesis, glutaminolysis, and mammalian target of rapamycin (mTOR) activation, are involved in the development of renal diseases by modulating the function and proliferation of Treg cells." (PMID 35251009, 2022). "Recently, growing evidence has demonstrated that the phosphatidylinositol 3-kinase (PI3K)/AKT/mammalian target of rapamycin (mTOR) signaling pathway plays an indispensable role in renal diseases to regulate autophagy." (PMID 35757387, 2021).
kidney disease (continued). "Activation of autophagy plays an important role against kidney diseases and the aging process, while sirtuins, mammalian target of rapamycin (mTOR), and AMP-activated protein kinase (AMPK) are the key regulators of autophagy." (PMID 34361023, 2021). "Although remarkable insights have been achieved over the last years, there is an ample room to improve our knowledge regarding the roles played by mTOR complexes and pathways in kidney physiology and pathogenesis of several renal diseases." (PMID 30510618, 2018). "Further study is needed to exploit more favorable therapeutic strategies for renal disease with mTOR inhibitors including rapalogues and ATP-competitive inhibitors of mTOR." (PMID 27338360, 2016). "When glomerular stress events eventually shift this balance toward increased mTOR expression and decreased autophagy activity, podocyte homeostasis is destroyed, leading to kidney diseases." (PMID 23667674, 2013). "The increase in mTOR mRNA in the remnant kidney model can play a key role in progression of renal disease." (PMID 22427849, 2012). "Our data are in accordance with the current views that tightly balanced mTOR activity is required in kidney homeostasis and the role of rapamycin in kidney diseases is context dependent." (PMID 22470459, 2012). "The aim of this study was to analyze the effects of delayed inhibition of mTOR pathway with low dose of everolimus on progression of renal disease and TGFβ expression in the 5/6 nephrectomy model in Wistar rats." (PMID 22427849, 2012). "The immunosuppressive mammalian target of rapamycin (mTOR) inhibitors are widely used in solid organ transplantation, but their effect on kidney disease progression is controversial." (PMID 22427849, 2012). "The mTOR pathway is being considered as a target pathway to treat kidney disease." (PMID 40129070, 2025). "By help of a genomic mouse model, highly purified podocytes were obtained from male and female mice with and without pharmacological challenge of the mechanistic target of rapamycin (mTOR) signaling pathway which is known to be deregulated in major kidney diseases." (PMID 39278930, 2024). "A large number of known kidney-disease related genes are newly identified to be sexually dimorphic and beyond classical sex hormonal effects further transcription factors were identified in sexually dimorphic response to mTOR inhibition with rapamycin." (PMID 39278930, 2024). "Remarkably, high number of previously reported kidney disease genes showed so far unknown intrinsic sexual dimorphism and/or different response patterns towards mTOR inhibition." (PMID 39278930, 2024). "The data reveal a so far unknown number of sexually dimorphic podocyte genes reported to be involved in the pathogenesis of kidney diseases and novel aspects of sexually dimorphic genomic and metabolic responses towards mTOR inhibition." (PMID 39278930, 2024). "We have also shown that the mTOR pathway is involved in podocyte differentiation and may also be involved in the podocyte deterioration that characterizes kidney diseases." (PMID 37973990, 2023). "Similarly, the use of rapamycin, an inhibitor of the mammalian target of rapamycin (mTOR), has been shown to have immunosuppressive and renoprotective effects in various animal models of kidney disease." (PMID 37371054, 2023). "Moreover, inhibition of ICR would attenuate fibrotic changes in TGF-β1-induced proximal tubular cells potentially through Akt/mTOR signaling pathway, which points to a novel anti-fibrotic treatment in renal diseases." (PMID 35688937, 2022). "Activation of the mTOR pathway is upregulated in renal diseases such as DN." (PMID 35251009, 2022). "Mammalian target of rapamycin (mTOR) signalling is involved in a variety of kidney diseases." (PMID 32086590, 2021).
kidney disease (continued). "Other subject to discuss is whether the mTOR activation was different in various renal diseases and whether mTOR activation could predict relapse with rejection in the baseline renal biopsies of donors in the non-rejection group." (PMID 33681239, 2021). "In renal disease, mTOR has been identified as a potential therapy target." (PMID 31485275, 2019). "However, considering the central participation of mTOR in the pathogenesis of other renal disorders, the use of rapamycin and its analogs meanwhile developed (rapalogues) everolimus and temsirolimus has been viewed as a promising pharmacological strategy." (PMID 30510618, 2018). "This article critically reviews the use of mTOR inhibitors in renal diseases." (PMID 30510618, 2018). "Notably, accumulated evidence suggests mTOR signaling deregulation as a central player in the pathophysiology of distinct kidney diseases." (PMID 30510618, 2018). "The mTOR pathway is an exciting area of research in many biomedical areas of knowledge, including aging, metabolism, neurobiology, oncobiology, and cardiovascular and renal diseases." (PMID 30510618, 2018). "mTOR inhibitors are useful for treating various renal diseases." (PMID 27338360, 2016). "Importantly, the mTOR (mammalian target of rapamycin) pathway as the crucial inhibitor of autophagy is upregulated in renal diseases, including ADPKD." (PMID 27231899, 2016). "Taken together, these data suggested the intriguing possibility that the severe kidney disorder in Phb2pko mice may be amenable to a therapeutic intervention with mTOR inhibitors." (PMID 25643582, 2015). "The aim of this study was to analyze the effects of delayed mTOR inhibition on progression of renal disease in the 5/6 nephrectomy model in Wistar rats, using a low dose of everolimus introduced 2 weeks after nephrectomy and to evaluate its effects on fibrosis mediators as TGFβ." (PMID 22427849, 2012). "Moreover, mTOR-independent autophagy-inducing pharmaceutical agents such as trehalose, geniposide, sarsasapogenin, sulforaphane, salvianolic acid B, hyperoside, metformin, which were also verified in some kidney diseases models." (PMID 36081940, 2022). "In renal diseases, T cells are involved in different abnormal metabolic pathways, such as increased oxidative stress, mitochondrial dysfunction, enhanced glycolysis, abnormal lipid synthesis, glutaminolysis, and highly activated mTOR, which all influence Treg cell proliferation and differentiation." (PMID 35251009, 2022). "Controversy exists about the beneficial effects of mTOR inhibition in experimental nephropathies with some reports showing that it may be useful to diminish progression and others reporting increase in proteinuria and aggravation of renal disease." (PMID 22427849, 2012). "Altered mTOR signalling was observed in cystic disease and fibrosis in rat models; mTOR kinase inhibitors (PP242, etc.)improved some renal disease end-points in rat studies." (PMID 41406476, 2025). "We were intrigued by the large amount of p-S6 seen in the TLTs and surrounding tubules in Atg7−/− kidneys, so next we determined the role of mTOR in TLT development and growth in two separate models of kidney disease, ADPKD and renal ischemia." (PMID 40496859, 2025). "Additionally, 71 pathways were found to be commonly enriched, including HIF-1α, VEGF, PI3K-Akt, mTOR, Rap1, PPAR, FcγR-mediated phagocytosis, T cell receptor, and regulation of actin cytoskeleton, which are related to kidney diseases." (PMID 40356949, 2025). "The mTOR-independent autophagy-regulating pathways, including JNK-beclin-1-PI3KC3 pathways, as well as the p38, NFkB, Akt, Ca2+-calpain, and cAMP-Epac-PLC-ε-IP3 pathways, are relevant to kidney diseases." (PMID 31382550, 2019).
neurodevelopmental disorder (82 papers, 2011 to 2026). A behavioral and cognitive disorder with onset during the developmental period that involves impaired or aberrant development of intellectual, motor, or social functions. "Knowledge around the genetics and neurobiology of neurodevelopmental disorders caused by mutations in genes in the mTOR pathway has expanded in recent years." (PMID 40426219, 2025). "Aberrant mTOR signaling is implicated in various neurodevelopmental disorders, including TSC, FCD, and Rett syndrome." (PMID 40365712, 2025). "Many neurodevelopmental disorders (NDDs) are associated with changes in the mechanistic target of rapamycin (mTOR) pathway." (PMID 40792287, 2025). "Abnormal PI3K-AKT/mTOR signaling is closely associated with the pathogenesis of several neurodevelopmental disorders." (PMID 38365306, 2024). "The mTOR pathway plays a critical role in brain development, and disruptions in mTOR signaling have been associated with neurodevelopmental disorders." (PMID 38928447, 2024). "More generally, pathogenic variants in other mTOR regulators can lead to similar neurodevelopmental disorders, as in TSC, collectively known as mTORopathies." (PMID 38540392, 2024). "We also used IUE, which allows us to express a plasmid of our choice that encodes constitutively active Rheb to increase mTOR activity, as reported in several neurodevelopmental disorders, and assess the impact of drug treatment on neuron morphology." (PMID 37620147, 2023). "Given the central role of mTOR in coordinating developmental cues and growth conditions, dysregulation of mTOR and its upstream regulators can cause disastrous neurodevelopmental disorders." (PMID 36440598, 2022). "Our findings have unveiled a crucial physiological function of the highly conserved UBE4B E3/E4 ligase in brain development and provide mechanistic insights into neurodevelopmental disorders associated with aberrant mTOR signaling." (PMID 36440598, 2022). "Although changes in the activity of the mTOR pathway are associated with numerous neurodevelopmental disorders, the molecular basis of disease development remains poorly understood." (PMID 34204880, 2021). "The pathogenicity of novel variants in MTOR in patients with neurodevelopmental disorders can be difficult to determine and the mechanism by which variants cause disease remains poorly understood." (PMID 34197453, 2021). "The dysregulation of transcriptional processes most likely contributes to disease development in neurodevelopmental disorders associated with changes in mTOR activity —yet mTOR-mediated transcriptional regulation in the brain has been poorly investigated." (PMID 34204880, 2021). "Mutations in mTOR pathway genes are linked to a variety of neurodevelopmental disorders and malformations of cortical development." (PMID 32876565, 2020). "Multiple neurodevelopmental disorders and malformations of cortical development are thought to arise due to the effects of mTOR signaling mutations on progenitor cells during fetal development." (PMID 32876565, 2020). "Dysregulation of mTOR is implicated in various neurodevelopmental disorders." (PMID 41244585, 2025). "This suggests that although the disease mechanism is understandably complex, misregulation of mTOR may play a major role in the neurodevelopmental disorders caused by the TTT mutations." (PMID 37175973, 2023). "Dysregulation of mTOR signaling is associated with a variety of neurodevelopmental disorders." (PMID 36440598, 2022). "mTOR and Nrf2 complexes are associated with external signals and transduction pathways and understanding the role of these complexes are necessary to develop future therapies for current neurodevelopmental disorders." (PMID 35805130, 2022). "Altered expression of these genes may be an important factor contributing to the pathogenesis of neurodevelopmental disorders associated with dysregulated mTOR signaling." (PMID 34204880, 2021).
neurodevelopmental disorder (continued). "The mechanistic target of rapamycin (mTOR) and ryanodine receptor (RyR) signaling pathways regulate fundamental processes of neurodevelopment, and genetic mutations within these pathways have been linked to neurodevelopmental disorders." (PMID 29201571, 2017). "Furthermore, our previous studies have revealed the potential involvement of abnormalities in MAP proteins (including MAP-Tau pathology) simultaneously with excessive mTOR activity in the molecular mechanisms underlying the pathogenesis of neurodevelopmental disorders, including ASD." (PMID 37108467, 2023). "Having in mind that mTOR signaling is an essential pathway during brain development and that mTOR dysregulation causes various neurodevelopmental disorders, dysregulation of metabolic gene expression may well contribute to neurological symptoms in mTOR-associated disorders." (PMID 34204880, 2021). "Ongoing research into mTOR inhibitors and modulators aims to explore their therapeutic potential for managing neurodevelopmental disorders and promoting brain health." (PMID 40365712, 2025). "mTORopathies, characterized by dysregulation of the mTOR signaling pathway, have emerged as a critical focus in the study of neurodevelopmental disorders and refractory epilepsy." (PMID 40358185, 2025). "More recent studies have shown that Tau protein pathology is also involved in several neurodevelopmental disorders, particularly those featuring hyperactivation of the mTOR pathway, including ASD." (PMID 37108467, 2023). "Taken together, these findings indicate that the mTOR-dependent autophagy is disrupted in these neurodevelopmental disorders." (PMID 34920755, 2021). "This suggests that the development of future therapies aimed at specifically targeting PPP2R5D-dependent effects on AKT/mTOR signaling in PPP2R5D-related neurodevelopmental disorder should be mindful of potential salutary effects." (PMID 33482199, 2021). "A thorough characterization of these different effects of mTOR dysregulation in human cortical development is therefore crucial to the creation of better disease models and therapies for multiple neurodevelopmental disorders." (PMID 32876565, 2020). "Several mutations in mTOR regulatory genes (e.g., TSC1, TSC2, LYK5/STRADA, AKT3, and DEPDC5) enhance activation of mTOR and lead to brain malformation and neurodevelopmental disorders." (PMID 29259984, 2017). "Defects in the rat sarcoma viral oncogene homolog (Ras)/extracellular-signal-regulated kinase and the phosphatidylinositol 3-kinase-mammalian target of rapamycin (mTOR) signaling pathways are responsible for several neurodevelopmental disorders." (PMID 26190969, 2015). "Her lack of response to sirolimus may represent the presence of a critical treatment window for mTOR inhibitors in neurodevelopmental disorders." (PMID 40206130, 2025). "Alterations in mTOR pathway signaling occur in numerous neurodevelopmental disorders." (PMID 40305300, 2025). "Notably, many of the significant miRNAs related to ACE exposure are linked to inflammatory/neuroinflammatory genetic pathways implicated in a variety of neurological and neurodevelopmental disorders (e.g., TGF-β, PI3K-Akt, and mTOR;)." (PMID 39596633, 2024). "As Tsc deletion produces a neurodevelopmental disorder, these discrepancies may depend on the role of mTOR in different types of cells and at different stages of development." (PMID 31978189, 2020). "Additional studies could determine whether inhibitors of mTOR or agonists of mGluR could be future therapeutics for those with neurodevelopmental disorders." (PMID 24795561, 2014). "Rapamycin and other mTOR inhibitors have been shown to be efficacious in the treatment of several TSC-associated tumors as well as seizures and may ameliorate the symptoms of neurodevelopmental disorders in adults." (PMID 28775826, 2017).